IFNG (interferon gamma)
Diseases named in the same sentence as IFNG in open-access papers (continued):
Sharing a sentence is not in itself a finding about the gene and the disease.
tumor (continued). "Upon binding to tumour cells, NK cells release interferon-γ (IFNγ) into the tumour microenvironment and cytolytic antibodies directly into the tumour cell." (PMID 36267157, 2022). "PLA2G2D, IFNG, CD8B and NKG7 were found to be significantly upregulated, which are associated with tumor immunity." (PMID 35530341, 2022). "Inflammatory cytokines such as IL-1β, TNFα, and IFNγ are produced to combat the initial tumor via activation of NF-κB, STAT1, and NLRP3 inflammasome pathways." (PMID 36555392, 2022). "An interesting possibility is that this is due to innate immune cells that produce inflammatory cytokines, including IFNγ, and are present in the tissue prior to tumor formation." (PMID 36531040, 2022). "Tumor progression can be promoted by these factors through various mechanisms, including IFNγ and IL-17 mediated tumor immune surveillance or the recruitment of immune cells into the tumor microenvironment via TNF-α, IL-1β, and IL-6." (PMID 36012113, 2022). "Lately, intensive investigation has been focused on Th17 cells, which effectively control tumor growth in an interferon-gamma (IFNγ)-dependent manner and exhibit increased persistence due to their “stem cell-like” phenotype." (PMID 35203357, 2022). "Expression levels ranged from the levels seen in IFNγ-induced wild-type fibroblasts (lane I) to the low levels that can be seen in some human tumor cell lines." (PMID 36389776, 2022). "In canine transmissible venereal tumour, the tumour regression phase is often associated with the upregulation of MHC-I and MHC-II molecules, mediated by factors such as IFNG from tumour-infiltrating lymphocytes." (PMID 36259237, 2022). "For this process to be optimal, a large number of engineered T cells should infiltrate tumor islets to produce a high amount of IFNγ acting on cancer cells." (PMID 36189315, 2022). "Lymphocytes from TDLNs resected during surgical operation were cultured with autologous-tumor cells for 2 weeks and evaluated tumor-reactivity by IFNγ ELISPOT assay." (PMID 35606862, 2022). "Monocyte from PBMCs were cultured in a medium with GM-CSF and IL-4, followed by pulsing with HOCl-oxidized whole tumor lysate and maturation with LPS and IFNγ." (PMID 36011029, 2022). "CD8+ CTLs can recognize specific antigen bound to major histocompatibility complex (MHC)-I on DC, then they were activated and can produce interferon γ (IFNγ), perforin, and granzyme B that contribute to tumor cell cytolysis." (PMID 35386705, 2022). "As an alternative indicator of systemic anti-tumor immunity, we profiled serum levels of two inflammatory cytokines, IFNγ and TNFα." (PMID 35780226, 2022). "Several posttranscriptional mechanisms have been reported to modulate IFNγ production in T cells, including tumor-infiltrating T cells." (PMID 34385592, 2022). "The poorly immunogenic or “cold” lesion of tumors contains cytotoxic lymphocytes (CTLs) with low expression of IFNγ and poor infiltration of CTLs into the tumor core, which are immunological ignorance." (PMID 35646111, 2022). "The latest reports in the literature suggest the anti-tumor activity of β-endorphins due to the activation of interferon gamma (IFN-gamma), granzyme-B, and perforin mediated by NK cells and macrophages." (PMID 36078233, 2022). "The tested candidates induced release of IL-2, granzyme B, perforin, and IFNγ from human PBMC in response to UACC-257 tumor cells." (PMID 35645207, 2022). "IFNγ-signaturehigh basal/squamous MIBC tumours had significantly enriched genomic damage from APOBEC enzymes." (PMID 36358715, 2022). "This novel vaccination method, but not control vaccination (irradiated B16-MRP1 cells decorated with unconjugated aptamers), elicited a strong immune response (increased T cell proliferation and IFNγ production) and inhibited subsequent tumor growth in vivo." (PMID 35141049, 2022).
tumor (continued). "Researchers believe that the main mechanism underlying this effect is that IFNγ released by CD8+ T cells downregulates the expression of SLC3A2 and SLC7A1 in tumor cells and inhibits the uptake of cystine by tumor cells." (PMID 34975326, 2022). "Interferon-gamma (IFN-γ) either was reported to stimulate or suppress the natural killer cell-mediated lysis of tumor cells derived from various pediatric tumor cell lines." (PMID 35974992, 2022). "Tumor-infiltrating CD8+ T cells are among the most abundant producers of IFNγ and critically contribute to antitumor immunity." (PMID 34385592, 2022). "CD8 + T cells in the tumor microenvironment can produce interferon-γ (IFNγ) to stimulate the up-regulation of PD-1/PD-L1 and IDO1 gene expression." (PMID 36059531, 2022). "Although the IFNG transcript itself can be detected in cancer cohorts, it shows weak sensitivity and, being a diffusible factor, IFNγ can elicit a response in the tumour even when originating from peritumoural leukocytes." (PMID 36358715, 2022). "Both cDC1s and cDC2s can acquire mregDC signature upon sensing or uptake of tumor-associated antigen, partially driven by IL-4 signaling and AXL signaling, whereas IFNγ is required for IL-12 production by mregDCs." (PMID 36031601, 2022). "What was reported, however, was impaired function in tumor infiltrating NK cells, with reduced IFNγ, TNFα, and proliferation." (PMID 35757002, 2022). "Similar to that observed in the spleen, p40 mAb treatment also upregulated human CD4+CD8+, CD4+IFNγ+ and CD8+IFNγ+ T cells in tumor tissues of PDX mice." (PMID 35053375, 2022). "EVs from the WT cells, but not TβRII null, led to a reduced cytotoxicity of tumor-infiltrating T cells (IFNγ+ or GZMB+ of CD8+ cells) and an increased exhaustion of tumor-infiltrating T cells (IFNγ+, PD1+ or TIM3+ of CD8+ cells)." (PMID 35915084, 2022). "The RNA-seq normalized expression values were used to compute the ratios of LAYN to GZMA and LAYN to IFNG for each tumor sample." (PMID 35197510, 2022). "Tumor and host immune cells release pro-cachectic cytokines such as tumor necrosis factor (TNFα), interleukin 1 (IL-1), IL-6, and interferon gamma (IFNγ)." (PMID 35326491, 2022). "Disruption of the CARMA1-BCL10-MALT1 signalosome complex in mature Tregs enhances the production of IFNγ in the tumor microenvironment, resulting in stunted tumor growth." (PMID 34385592, 2022). "Meanwhile, Anlotinib treatments still suppressed tumor growth effectively in Ifnγ knockout mice compared with the vehicle control group." (PMID 35990640, 2022). "It has been demonstrated that interferon-gamma (IFN-γ), cytolytic activity, and angiogenesis serve as indicative biomarkers in anti-tumor response and cancer progression." (PMID 36193203, 2022). "Acute IFNγ exposure likely results in the activation of an anti-tumor immune response (the recruitment and activation of antigen-presenting cells, T cell priming and activation, NK cell activation, and tumor cell killing)." (PMID 36551577, 2022). "Consistently, RNA seq analysis of MC38 tumor tissues showed AN3025 treatment elevated expression of immune activation genes such as ifn (gene for IFNγ) and gzmk (gene for Granzyme K)." (PMID 35251028, 2022). "IL-33 induces CD40L expression by tumour infiltrating lymphocytes which promotes IFNγ+ production by NK cells and T cells." (PMID 36263033, 2022). "Inactivation of STUB1 increased tumour cells’ sensitivity for IFNγ, which in turn upregulated ISGs expression and enhanced antigen processing and presentation in vitro." (PMID 35982220, 2022). "For example, IFNγ increases the production of the CXCR3 ligands CXCL9-11 by tumor cells, and correlates with an increase in NK cells in subcutaneous tumors and improved survival in mice." (PMID 35844626, 2022).
tumor (continued). "Tumor-specific T-cell-induced IFNγ can induce lethal anti-tumor immunity by promoting tumor antigen presentation, recruiting of other immune cells, and directing anti-proliferative and pro-apoptotic effects toward the tumor cells." (PMID 36142818, 2022). "As tumor-reactive immune cells are thought to be a main source of IFNγ in the tumor microenvironment, PD-L1 mRNA expression also significantly correlated with the lymphocyte score." (PMID 34268602, 2022). "Regarding IFNγ expression, we noticed similar trends of increasing levels in tumour tissue upon EGFR inhibition in the erlotinib-treated mice." (PMID 36010935, 2022). "The activated Vδ2 T cells are cytolytic against tumor cells, secrete the inflammatory cytokines TNFα and IFNγ among others, release cytolytic proteins perforin and granzyme B, and are effector cells for antibody-dependent cell mediated cytotoxicity (ADCC)." (PMID 36275712, 2022). "We next stained the 36 tumor specimens for IFNγ by immunohistochemistry and found that IFNγ expression localized predominantly to the CD3+ T-cell infiltrate, with some staining also co-localizing CK19 and E-Cadherin-expressing epithelial tissues." (PMID 35155243, 2022). "The M1 phenotype is activated by Toll-like receptor ligands, and interferon gamma (IFN-γ), produces tumor cytotoxicity by producing pro-inflammatory cytokines such as TNF-α and IL-1β, and inhibits tumor progression." (PMID 35740547, 2022). "This enhancement in CTL trafficking, in combination with increased class-I HLA expression within the TME, promotes effector–tumor cell interactions that increase granzyme B, IFNγ, and TIS gene expression." (PMID 36923305, 2022). "Tumor recognition was measured by degranulation (CD107a expression) and IFNγ production analyzed by flow cytometry." (PMID 35433456, 2022). "Activated γδ T-cells display strong cytotoxic activity through the release of granzyme B and perforin, by membrane bound TRAIL and Fas (CD95) ligands or production of IFNγ or TNFα to amplify the immune response, thereby counteracting tumor development." (PMID 35784326, 2022). "We found higher probability of activation of anti-tumor IFNα and IFNγ pathways and lower probability of activation of the pro-tumor TGFβ pathway in the “CISH-up” class, as compared to the “CISH-down” class." (PMID 35884417, 2022). "The tumor-infiltrating CD8 T cells kill the tumor cells by releasing apoptosis-inducing cytotoxic proteins (e.g. interferon gamma, IFN- γ) or granules (e.g. perforin and granzyme B)." (PMID 35756611, 2022). "CXCL10 activates anti-tumor immunity by inducing interferon gamma, and inhibits angiogenesis and prevents tumor growth." (PMID 35223493, 2022). "For example, interferon-gamma/alpha response was positively correlated with macrophages in all three tumor types." (PMID 35469013, 2022). "Th1 cells produce tumor necrosis factor alpha (TNF-α), interferon gamma (IFN-γ), interleukin (IL)-2 and IL-12 to mediate antitumor effects, while Th2 cells produce IL-4 and IL-10 which favor tumor growth." (PMID 35805995, 2022). "DCR following treatment was 71%, in association with improved IFNγ production, CXCL9/CXCL10 chemokine expression and increased intra-tumor T cell infiltration, all representative of an immune-stimulatory environment." (PMID 36428727, 2022). "Immune checkpoint inhibitor treatment activates CD8+ T cells to produce interferon gamma (IFNγ) and promotes ferroptosis in tumor cells." (PMID 35847985, 2022). "As an emerging paradigm, intact IFNγ sensing in tumours leads to adequate antigen presentation and T cell recognition, but also upregulates programmed death ligand 1 (PD-L1) to confer immunoevasion." (PMID 35982220, 2022). "In contrast, among ECs the opposite was the case; that is, MSI tumours had significantly lower IFNγ pathway activity (p = 2.3e‐03)." (PMID 35262923, 2022).
tumor (continued). "Since PD-L1 expression significantly correlated with tumor immune infiltration, IFNγ released from infiltrating immune cells is probably the main inducer of PD-L1 in the tumor microenvironment." (PMID 34268602, 2022). "While Th1 cells can be an important source of IFNγ, these cells can be functionally altered in the tumor microenvironment." (PMID 34385592, 2022). "Here, we detected a series of tumor-related gene sets, such as E2F targets, Myc targets, G2/M checkpoint, pancreas beta cells and interferon-gamma response." (PMID 35449086, 2022). "The activation of infused CAR T cells and interaction with tumor cells leads to the release of several cytokines including IL-2, soluble IL-2Rα, IFNγ, IL-6, tumor necrosis factor (TNF)-α, soluble IL-6R, and GM-CSF." (PMID 35845425, 2022). "The IFIT1, ISG15, IFITM1 and IFI27 genes are related to activation of the interferon gamma (IFNγ) response, suggesting possible inflammatory responses in NR tumour samples." (PMID 35053540, 2022). "Low concentrations of IFNγ upregulated PD-L1 in tumor cells in vitro, even when administered alongside high concentrations of TGFβ." (PMID 35155243, 2022). "Local immunity was evaluated by quantitative real-time RT-PCR, which revealed that tumour regression was associated with increased expression of CD8 and IFNγ." (PMID 36140243, 2022). "The frequency of Vδ2 T cells expressing IFNγ was higher when tumor cells were cultured with LV-shFDPS-IL2 (16.6%) compared to tumor cells transduced with LV-shFDPS (10.7%)." (PMID 36275712, 2022). "Among other, the level of IFNγ, a cytokine that is critical to sustain anti-tumor responses, was dramatically lower in the serum of infected mice compared to non-infected counterparts." (PMID 35677057, 2022). "Overall survival for basal/squamous tumours (pooled from TCGA-BLCA and Lund cohorts) was significantly lower in tumours with a weak IFNγ-signature." (PMID 36358715, 2022). "In the early stage of tumors, the production of IFNγ by Th1 cells induces an M1 phenotype for TAM with anti-tumor properties." (PMID 35163420, 2022). "Significantly lower percentages of CD3 + T cells expressing the inflammatory cytokines IFNγ and TNFα were detected in S2 and S3 tumours than S1 tumours." (PMID 35301339, 2022). "The JAK-STAT pathway is also important in IFNγ function, as seen in host defense against pathogens, inflammatory and immune responses, tissue damage, and tumor immunosurveillance." (PMID 35372046, 2022). "The platelet-derived growth factor (PDGF) secreted by tumor cells can be recognized by NKp44 triggering NK cell secretion of interferon-gamma and tumor necrosis factor-alpha to hamper tumor growth." (PMID 36359863, 2022). "Upon closer observation, it was seen that CD4+IFNγ+ population was clearly segregated in two populations based on the number of these cells per gram of tumor." (PMID 35651802, 2022). "While ex vivo acetate treatment increased IFNγ production by exhausted T cells, reducing ACSS expression in T cells impaired IFNγ production by TILs and prevented tumor control." (PMID 35203357, 2022). "The 63 upregulated genes, including PLA2G2D, IFNG, LAG3, CD8B and NKG7, were associated with tumor immunity." (PMID 35530341, 2022). "CD8+ cytotoxic T cells and its secreted interferon gamma are central to the tumor immune elimination, and increased immune cell infiltration indicates prominent immune response, but these do not necessarily lead to better tumor control or survival." (PMID 36092894, 2022). "To investigate cytokine secretion profiles of 28z/IL-7-CAR-T cells against Raji cells, we measured the IFNγ and TNFα response after co-culturing with tumor cells using flow cytometry." (PMID 35869100, 2022). "In response, T cells are able to overcome tumour-induced tolerance and produce IFNγ and IL-12 for the initiation of anti-tumour immunity." (PMID 35454819, 2022).
tumor (continued). "Given the metabolic complexity of the TME, mouse lymphomas overexpressing the glycolytic/glutaminolytic transcription factor Myc were shown to generate fewer tumor-resident IFNγ+ NK cells." (PMID 34239083, 2022). "ICIs activate the effector function of cytotoxic T-cell-driven antitumor response to release interferon gamma (IFNγ), which induces ferroptosis in tumor cells." (PMID 35882850, 2022). "Induction of PD-L1 in monocytes and DC occurs via IFNg, and PD-L1 exerts tolerogenic, immunosuppressive functions to support tumor growth." (PMID 35493454, 2022). "Playing a dual role in tumor suppression and pro-tumorigenesis in human cancers, interferon gamma is engaged in complex tumor immune regulatory mechanisms and is associated with the immune microenvironment and prognosis of BC." (PMID 36672769, 2022). "The use of a PI3Kγ inhibitor reverses this partially due to the upregulation of IFNγ which signals TAMs to revert back to an M1 phenotype, thereby promoting anti-tumor immunity." (PMID 36031601, 2022). "Alternatively, the Co treatment, alone or with A, resulted in much lower frequency of CD4+ or CD8+ T cells with TNFα, and even more so IFNγ production in the tumor (CD4+ IFNγTNFα+: Co/A=17.2 ± 3.1, Ca/N=31.8 ± 4.1, p=0.0097)." (PMID 36419897, 2022). "This was also in line with enhanced activation of the IFNα and IFNγ activation pathways, two cytokines with anti-tumor activity, in “CSPG4-high” tumors (respectively, p = 6.46 × 10−3 and p = 3.23 × 10−3)." (PMID 35267618, 2022). "Loss of IFNγ and MHC-I signatures are frequently observed in human tumours that can cause unresponsiveness to immunotherapy." (PMID 36230680, 2022). "IFNγ is a cytokine that mediates various immunomodulatory effects including direct anti-tumor effects, but also enables NK cells to shape subsequent adaptive immune responses." (PMID 36275693, 2022). "Examination of cytokine levels in tumor-bearing mice on post-inoculation day 21 showed that inoculation of ATX-KO B16-F10 cells led to a selective increase in IFNγ and TNFα levels only in Sftpc-KO mice." (PMID 35326737, 2022). "Type II IFN (IFNγ) is thought to play a crucial role in cancer immunosurveillance, with the ability to promote anti-tumor immunity by increasing tumor immunogenicity." (PMID 36212161, 2022). "Consistent with the Vβ5-dependent cytotoxicity, Vβ5-CAR-T cells produced more IFNγ when cocultured with Vβ5-positive CCRF-CEM or Hut-78 tumor cells." (PMID 35882880, 2022). "On the other hand, IFNγ directly initiate arachidonic acid-induced tumor cell ferroptosis via activating ACSL4." (PMID 35882850, 2022). "They inhibit tumor growth by producing interferon gamma, subsequently leading to angiostasis, cell cycle inhibition, apoptosis and tumor phagocytosis by macrophages." (PMID 36741710, 2022). "As a result, IFNγ is abundantly secreted in to the tumor microenvironment, which further promotes ferroptosis." (PMID 35531466, 2022). "An acidic pHe and a high concentration of lactate together lead to a decrease in the activity of natural killers, including the depletion of interferon gamma (IFN-γ) and their ability to infiltrate the tumor." (PMID 36106097, 2022). "Altogether, these data show that IFNγ production by CD4 T cells upon antigen encounter on TAM in the tumor microenvironment is responsible for both the TAMs functional switch and the antitumor effect." (PMID 35903540, 2022). "CD8+ CTLs are considered important players in anti-tumor immune responses that recognize tumor antigens and mediate tumor-killing effects via, e.g., pro-inflammatory interferon γ (IFNγ) and cytotoxic granzyme or perforin." (PMID 35626676, 2022). "Simultaneously, our findings highlight that a more granular understanding of IFNγ signaling (or modulation thereof) will be necessary to fully exploit the anti-tumor effects of STUB1 inhibition, in combination with ICB treatment." (PMID 35395848, 2022).